MYSM1 (Myb like, SWIRM and MPN domains 1)
Diseases named in the same sentence as MYSM1 in open-access papers (continued):
Sharing a sentence is not in itself a finding about the gene and the disease.
anemia (6 papers, 2015 to 2025). A reduction in the number of red blood cells, the amount of hemoglobin, and/or the volume of packed red blood cells. "BMF secondary to mutations in Myb-like SWIRM and MPN domains (MYSM1) were first identified in two siblings who presented with anemia and facial dysmorphism, and have been more widely characterized by subsequent studies." (PMID 40535318, 2025). "A 15-year-old female patient with BMFS caused by a mutation in MYSM1 presented initially at the age of 4 months with anemia." (PMID 40535318, 2025). "Loss-of-function variants in the MYSM1 gene, which is a regulator of transcription, present with transfusion-dependent refractory anemia in early childhood in addition to mild thrombocytopenia and low NK- and B-cell counts." (PMID 38002903, 2023). "Overall, the reported anemia and leukopenia phenotypes of Mysm1DN/DN mice are highly consistent with those observed in the Mysm1−/− mouse model, and also clinically in the patients with MYSM1 loss-of-function mutations." (PMID 36611064, 2023). "Additionally, a sixth patient also carrying the p.E390* MYSM1 mutation in a homozygous state was reported to have neutrophilic panniculitis, as well as reduced B cell count, anemia, and a mild growth retardation." (PMID 32344625, 2020). "Importantly, mutations in MYSM1 in human were recently linked to a rare hereditary disorder characterized by leukopenia, anemia, and other hematopoietic and developmental abnormalities." (PMID 32344625, 2020). "Finally, a novel homozygous mutation p.R478* in MYSM1 was recently identified via whole-exome sequencing in a patient diagnosed with Diamond-Blackfan anemia, a disorder characterized by anemia and to a lesser extent other hematological and developmental abnormalities." (PMID 32344625, 2020). "Homozygous or compound heterozygous MYSM1 mutations in rare human patients result in an inherited bone marrow failure syndrome (IBMFS), characterized by anemia, leukopenia, and in some cases growth delay and mild developmental abnormalities." (PMID 36611064, 2023). "We conducted further hematology analyses on tamoxifen-treated CreERT2 transgenic mice of Mysm1+/fl, Mysm1fl/fl, and Mysm1DN/fl genotypes, and observed highly similar hematopoietic phenotypes in the Mysm1Δ/DN mice, including macrocytic anemia, leukopenia, and lymphocyte depletion." (PMID 36611064, 2023).
bone marrow failure syndrome (6 papers, 2017 to 2025). "Biallelic MYSM1 variants are linked to rare bone marrow failure syndromes, presenting with cytopenia, B-cell deficiency, hypogammaglobulinemia, and developmental abnormalities." (PMID 40535318, 2025). "Rare MYSM1 mutations in human patients result in an inherited bone marrow failure syndrome, highlighting the biomedical significance of MYSM1 in the hematopoietic system." (PMID 36611064, 2023). "MYSM1 mutations in patients with an inherited bone marrow failure syndrome (IBMFS) highlight the biomedical importance of understanding MYSM1 activities and functions." (PMID 32344625, 2020). "Inactivating MYSM1 mutations cause an inherited bone marrow failure syndrome (IBMFS)." (PMID 39108012, 2024). "The discovery of MYSM1 mutations in patients with a hereditary developmental and bone marrow failure syndrome raises strong interest in understanding the MYSM1-regulated checkpoints in mammalian physiology and the underlying molecular mechanisms of MYSM1 activity in these systems." (PMID 32344625, 2020). "In human hematopoiesis, similar functions of MYSM1 may be required because rare inactivating MYSM1 mutations were associated with inherited bone marrow failure syndromes." (PMID 28978033, 2017).
colorectal cancer (6 papers, 2017 to 2024). A primary or metastatic malignant neoplasm that affects the colon or rectum. "In colorectal cancer, a lower MYSM1 expression is observed, and its high expression correlates with a favorable prognosis." (PMID 39684760, 2024). "In colorectal cancer, a lower MYSM1 expression correlates with a better prognosis, as it epigenetically upregulates the miR-200 family and CDH1, subsequently suppressing the PI3K/AKT pathway." (PMID 39684760, 2024). "It has been reported that MYSM1 suppresses colorectal cancer progression via histone H2A deubiquitination, thereby activating miR-200 family members/CDH1." (PMID 38177530, 2024). "The role of MYSM1, a metalloprotease that deubiquitinates monoubiquitinated histone H2A, in colorectal cancer was identified to evaluate its potential clinical application value." (PMID 34706761, 2021). "Herein, we aimed to examine the expression level of MYSM1 in tumor tissues and its correlation with clinicopathology and survivals of patients with colorectal cancer (CRC).MYSM1expressions in tumor specimens resected from 123 CRC patients were detected by immunochemistry and Western blot analysis." (PMID 28498834, 2017). "Mechanistic studies indicate that MYSM1 may epigenetically enhance the expression of the miR-200 family and CDH1, thus inhibiting the PI3K/AKT signaling pathway and reducing the progression of colorectal cancer." (PMID 39684760, 2024).
breast carcinoma (5 papers, 2022 to 2025). "In this study, we provided the evidence to show that MYSM1 is required for the association between the HATs complex and ERα, modulating active histone modifications to enhance chromatin accessibility in a serial and combinatorial manner in the breast cancer cellular context (D and EV1B)." (PMID 38177530, 2024). "Silencing MYSM1 inhibits the increase of breast cancer-derived cells in xenograft models and increases their sensitivity to anti-estrogens." (PMID 40244377, 2025). "MYSM1, a deubiquitinase highly expressed in breast cancer samples, was shown to regulate ERα activity, and its depletion in xenograft models reduced breast cancer cell proliferation while enhancing sensitivity to anti-estrogen therapies." (PMID 40244377, 2025). "In this study, we identified a histone deubiquitinase, MYSM1 as a novel ERα co-activator in breast cancer." (PMID 38177530, 2024). "qPCR results in 9 pairs of breast cancer individuals also showed an internal consistency of the transcriptional level of MYSM1 as its mRNA levels are higher in the tumor group." (PMID 38177530, 2024). "Taken together, these results demonstrated that MYSM1 depletion suppressed the breast cancer cell growth in mice." (PMID 38177530, 2024). "To sketch out the clinical relevance of MYSM1 in breast cancer, we took advantage of the commercial tissue microarrays as well as some paraffin sections owing detailed patient information sponsored by hospital." (PMID 38177530, 2024). "MYSM1 was identified as an ERα co-activator that participates in ERα signaling regulation and is antagonistic to endocrine sensitivity in ERα-positive breast cancer (BCa)." (PMID 38177530, 2024). "MYSM1 expression was drastically decreased in breast cancer, especially in TNBC, suggesting a potential anticancer effect." (PMID 35217648, 2022). "Virtual screening identified Imatinib as a small molecule capable of interacting with the catalytic MPN domain of MYSM1, and this effectively inhibited breast cancer cell growth, highlighting the MYSM1-ERα axis as a promising target to overcome endocrine independence in breast cancer." (PMID 40244377, 2025). "The regulation function of MYSM1 on ERα-induced transactivation indicates that MYSM1 acts as a novel ERα co-activator, suggesting that MYSM1 may play an important role in breast cancer." (PMID 38177530, 2024). "Our study suggests that MYSM1 as a deubiquitinase is involved in up-regulation of ERα action, exerting epigenetic modifier and ERα stability maintainer to enhance antiestrogen insensitivity in ERα positive breast cancer." (PMID 38177530, 2024). "We further demonstrate that MYSM1 associates with ERα and increases ERα-induced transcriptional activity through non-histone and histone deubiquitination in breast cancer-derived cell lines." (PMID 38177530, 2024). "This prompted us to ask how MYSM1 influences ERα protein expression in breast cancer." (PMID 38177530, 2024). "Above all, these results implied that Imatinib could exert its inhibitory action on breast cancer cell proliferation through the MYSM1-ERα axis." (PMID 38177530, 2024). "Additionally, an increased MYSM1 expression has been observed in estrogen receptor-alpha (ERα)-positive breast cancer (BCa) clinical samples." (PMID 39684760, 2024). "Collectively, our data have demonstrated the function of MYSM1 on maintenance of ERα stability and modulation of ERα action to confer antiestrogen insensitivity in ERα-positive breast cancer, providing a potential therapeutic target for endocrine resistance in ERα-positive BCa." (PMID 38177530, 2024). "Given its pleiotropic biological functions, MYSM1 may be a potential therapeutic target for drug development against breast cancer, especially in endocrine resistant ERα-positive breast cancer." (PMID 38177530, 2024). "The data showed that higher expression of MYSM1 exhibited the poor overall survival, implying that MYSM1 may act as an indicator in breast cancer prognosis." (PMID 38177530, 2024).
breast carcinoma (continued). "MYSM1 protein is prominently up-regulated in breast cancer cohort." (PMID 38177530, 2024). "To investigate the subcellular distribution of MYSM1 and ERα, we applied immunofluorescence (IF) in HEK293 cells and breast cancer cells (MCF-7 and T47D) (I and EV1F)." (PMID 38177530, 2024). "Herein, we provided the evidence to show that MYSM1 co-activates ERα action via histone and non-histone manner to confer antiestrogen insensitivity in breast cancer." (PMID 38177530, 2024). "Thus, MYSM1 enhances ERα action via histone and non-histone deubiquitination to promote cell proliferation and antiestrogen insensitivity in breast cancer progression." (PMID 38177530, 2024). "On the other hand, our results also demonstrated that MYSM1 accelerates cell proliferation even in the absence of E2, suggesting that MYSM1 may also participate in regulating non-canonic ERα signaling pathway independent on E2 treatment to participate in promoting breast cancer process." (PMID 38177530, 2024).
lymphoma (5 papers, 2015 to 2021). A malignant (clonal) proliferation of B- lymphocytes or T- lymphocytes which involves the lymph nodes, bone marrow and/or extranodal sites. "To further establish the protective effect of MYSM1‐loss on lymphoma disease progression, we employed an adoptive lymphoma cell transfer model." (PMID 34114734, 2021). "This indicates that the loss of MYSM1 can inhibit the oncogenic activity of cMYC and delay the onset of fatal lymphoma." (PMID 34114734, 2021). "A reduction in the translation factor eEF1G in EuMyc Mysm1‐/‐ lymphoma cells was further validated by flow cytometry at the protein level." (PMID 34114734, 2021). "Second, in a previous study, an increased incidence of lymphoma was observed in Mysm1 knockout mice." (PMID 34706761, 2021). "We observed a significant down‐regulation in the expression of genes encoding ribosomal proteins and translation factors in EuMyc Mysm1‐/‐ relative to control EuMyc lymphoma cells." (PMID 34114734, 2021). "Correspondingly, on the mRNA level, MYSM1 was expressed in human PBMC and in lymphoma and leukemia cell lines to variable extents." (PMID 32466590, 2020).
viral infection (5 papers, 2018 to 2022). "For example, viral infection can cleave K63-linked ubiquitin chains from STING by increasing MYSM1 levels or enhancing the recruitment of PPM1G to dephosphorylate STING." (PMID 36189363, 2022). "Mysm1-/- macrophages therefore showed enhanced production of inflammatory cytokines and type-I interferons, and mice with either systemic or myeloid lineage-restricted Mysm1-deletion were more susceptible to septic shock and peritonitis, but showed enhanced clearance of viral infections." (PMID 32344625, 2020). "MYSM1-/- mice show a hyper-inflammatory immune response, acute tissue damage, and higher mortality than WT mice upon virus infection." (PMID 33643304, 2020). "The deubiquitinases OTUB1/2, UCHL1, MYSM1 and DUBA inhibit K63-linked ubiquitination of TRAF3 or TRAF6 and negatively regulate IFNs production during viral infection." (PMID 29734366, 2018). "Similarly, it has been reported that some deubiquitinases including OTUB1/2, UCHL1, MYSM1 and DUBA can remove K63-linked ubiquitination of either TRAF3 or TRAF6, thus inhibiting IFNs production during viral infection." (PMID 29734366, 2018). "In addition, MYSM1 interacts with STING to cleave STING ubiquitination and attenuate the pathway, and MYSM1-deficient mice exhibit tissue damage and high mortality upon virus infection." (PMID 34707613, 2021). "The Myb-like, SWIRM, and MPN domains 1 protein (MYSM1, a metalloprotease, which deubiquitinates the K119-monoubiquitinated form of the H2A) is another cGAS-STING negative regulator that upregulates after viral infection and intracellular DNA stimulation." (PMID 33643304, 2020).
bone marrow failure (4 papers, 2018 to 2023). "Homozygous missense and nonsense variants leading to MYSM1 deficiency have previously been reported in patients presenting with bone marrow failure and B cell lymphopenia." (PMID 34539671, 2021). "Third, using genome-wide homozygosity mapping and WES, we demonstrated MYSM1 (OMIM 612176) mutations in two siblings who presented with congenital bone marrow failure and myelodysplasia." (PMID 30697212, 2018).
depression (4 papers, 2022 to 2025). "This study underscores the vital function of MYSM1 in the nervous system and emphasizes astrocytic MYSM1 as a potential risk factor for depression and a promising therapeutic target." (PMID 39684760, 2024). "Our previous research revealed the important function of Mysm1 in the brain, highlighting astrocytic Mysm1 as a potential risk factor for depression and as a valuable target for drug discovery to treat depression." (PMID 38342917, 2024). "The study reveals, for the first time, the important function of Mysm1 in the brain, highlighting astrocytic Mysm1 as a potential risk factor for depression and as a valuable target for drug discovery to treat depression." (PMID 36414403, 2022). "Our previous study indicated that Mysm1 was highly expressed in the hippocampus, internal capsule, frontal lobe, and temporal lobe brain sections from patients with severe depression." (PMID 40344568, 2025). "Recent studies have demonstrated that MYSM1 expression is substantially increased in the brains of both depression patients and mice displaying depressive-like behaviors." (PMID 39684760, 2024). "Aberrant expression of Mysm1 leads to different diseases, including bone marrow failure disorder, autoimmune diseases, cancer, and depression." (PMID 38342917, 2024). "As expected, the mice with LPS‐induced depression also showed significant Mysm1 upregulation in the MHb, HIP, and IC compared with their saline group." (PMID 36414403, 2022). "In the present study, we demonstrated that deubiquitinase Mysm1 was induced in the brain tissues from patients with major depression and mice with depressive‐like behaviors." (PMID 36414403, 2022). "Deubiquitinase Mysm1 is induced in the brain tissues from patients with major depression and from mice with depressive behaviors." (PMID 36414403, 2022). "In this study, it is observed that deubiquitinase Mysm1 is induced in the brain tissues from patients with major depression and from mice with depressive behaviors." (PMID 36414403, 2022). "Hopefully, reducing astrocytic Mysm1 expression to alleviate depression in mice will also be an ideal strategy in humans suffering from depressive disorders." (PMID 36414403, 2022). "In this study, we revealed that Mysm1 was significantly upregulated in the brain tissues from patients with major depression and mice with depressive‐like behaviors." (PMID 36414403, 2022). "Together, these results provide evidence that there is a distinct role for Mysm1 in regulating astrocytic function in depressive disorders." (PMID 36414403, 2022). "This review provides a comprehensive overview of MYSM1’s deubiquitination functions in regulating stem cell and immune cell activities, and its involvement in cancer, aging, and depression, providing valuable insights for future comprehensive research in the MYSM1 field." (PMID 39684760, 2024). "This review comprehensively details MYSM1’s deubiquitinating activities in both the nucleus and cytoplasmic compartments, its effects on stem cell proliferation, differentiation, and immune cell function, and its involvement in cancer, aging, and depression." (PMID 39684760, 2024). "To test whether Mysm1 upregulation is universal in depression, we examined mice in which depression was induced by treatment with lipopolysaccharide (LPS)." (PMID 36414403, 2022). "Interestingly, Mysm1 was highly expressed in the hippocampus, internal capsule, frontal lobe, and temporal lobe brain sections from patients with severe depression and in the MHb, HIP, or IC of depressive mice." (PMID 36414403, 2022). "Collectively, the data indicated that pharmacological drugs that suppress Mysm1 expression may be good candidates for depression therapy." (PMID 36414403, 2022).
depression (continued). "The role of both genetic and pharmacological agents in the inhibition of astrocytic Mysm1 to alleviate depressive‐like disorders suggests that astrocytic Mysm1 may be a valuable target for drug discovery in depression." (PMID 36414403, 2022). "Our findings demonstrate that repressing Mysm1 expression could relieve depression‐related behaviors." (PMID 36414403, 2022). "Suppression of Mysm1 expression could alleviate depressive disorders by promoting ATP production." (PMID 40344568, 2025). "Suppression of Mysm1 expression could relieve depressive disorders by promoting ATP production." (PMID 36414403, 2022). "MYSM1 is involved in regulating various types of diseases, such as inherited bone marrow failure syndrome (IBMFS), cancer, aging, and depression." (PMID 39684760, 2024).